PKP3 (plakophilin 3)
Diseases named in the same sentence as PKP3 in open-access papers (continued):
Sharing a sentence is not in itself a finding about the gene and the disease.
nasopharyngeal carcinoma (2 papers, 2021 to 2024). A carcinoma arising from the nasopharyngeal epithelium. "The loss of PKP3 in both nasopharyngeal carcinoma (NPC) and OSCC were associated with tumor progression and metastasis." (PMID 34203070, 2021).
pancreatic adenocarcinoma (2 papers, 2011 to 2023). "In accordance with the gene expression levels observed in TCGA pancreatic adenocarcinoma specimens, we screened PKP3 co-expressed genes among a number of 19,296 genes." (PMID 37760912, 2023).
pancreatic cancer (2 papers, 2022 to 2023). "The current investigation evaluated the predictive significance and underlying processes of PKP3 within pancreatic cancer (PC) tissues." (PMID 37760912, 2023).
squamous cell carcinoma (2 papers, 2022). A carcinoma arising from squamous epithelial cells. "PKP3 can also mediate the assembly of desmosomes and promote E-Cadherin maturation through Rap1 GTPase in squamous cell carcinoma (SCC) 9 cells because the lack of Pkp3 disrupts the E-Cadherin/Rap1 complex, which is a necessity for adherens junctions." (PMID 36291586, 2022).
alopecia (1 paper, 2017). Hair loss usually from the scalp. "Pkp3 deficient mice develop an abnormal hair coat and secondary alopecia." (PMID 28228108, 2017).
atopic dermatitis (1 paper, 2015). "Because of this dermatitis associated muscle wasting, the PKP3 null mice are smaller in size than the wild type mice and are very similar to the mouse model for atopic dermatitis, a severe form of skin inflammation." (PMID 25875355, 2015).
colorectal adenocarcinoma (1 paper, 2019). The most common type of colorectal carcinoma. "A molecular interaction between Armc8 with Pkp3 was confirmed by co-immunoprecipitation of the endogenous proteins from human colorectal adenocarcinoma cells SKCO-15." (PMID 30482882, 2019).
colorectal cancer (1 paper, 2015). A primary or metastatic malignant neoplasm that affects the colon or rectum. "It was observed that a thorough immuno-histochemical analysis of PKP3 and MMP7 levels in a large dataset of colorectal cancer patients has not been performed to determine if any correlation exists between PKP3 and MMP7 levels." (PMID 25875355, 2015).
dermatitis (1 paper, 2015). An inflammatory process affecting the skin. "Under normal conditions, young PKP3-/- mice, of the age of 3 weeks develop epidermal hyperplasia, severe skin inflammation and hair loss." (PMID 25875355, 2015).
ectodermal-dysplasia (1 paper, 2012). "Increased skin fragility was accompanied by a decrease in the number and size of basally disposed desmosomes within the ectoderm, consistent with prior Pkp3 depletion studies, and studies of patients with Pkp1 mutations that exhibit skin fragility ectodermal-dysplasia." (PMID 22496792, 2012).
enterocolitis (1 paper, 2023). An inflammatory process affecting the small intestine and colon. "Variants of SIGIRR/PKP3/TMEM16J lead to severe inflammatory diseases such as pneumonia, enterocolitis, and kidney graft rejection." (PMID 36520003, 2023).
gastric adenocarcinoma (1 paper, 2011). "In our study on gastric adenocarcinoma, loss of PKP3 expression inversely correlated with nodal status and stage." (PMID 21194493, 2011). "The results of this study suggest that loss of PKP2 and PKP3 proteins may have significant role in the prognosis of gastric adenocarcinoma, however further invastigation including larger case series is needed." (PMID 21194493, 2011). "In summary, present study has identified the significantly decreased PKP2 and PKP3 immunoreactivity in gastric adenocarcinoma." (PMID 21194493, 2011).
keloid (1 paper, 2022). An irregularly shaped, elevated mark on the skin caused by deposits of excessive amounts of collagen during wound healing. "Moreover, several proteins that play a role in cell junctions were also downregulated in keloids, including EVPL, PPL, DSP, PKP1, PKP3, DSC1, DSG1, and FLG." (PMID 35435317, 2022).
kidney chromophobe (1 paper, 2023). "Nevertheless, patients diagnosed with kidney chromophobe, kidney renal clear cell carcinoma, and liver hepatocellular carcinoma exhibited a significant decrease in PKP3 mRNA expression." (PMID 37760912, 2023).
Lewis lung carcinoma (1 paper, 2021). "The inhibition of circIGF2BP3/PKP3 enhanced the treatment efficacy of anti-PD-1 therapy in a Lewis lung carcinoma mouse model." (PMID 34416901, 2021).
metastatic melanoma (1 paper, 2018). A melanoma that has spread from its primary site to another anatomic site. "Our study found that genes involved in the biological processes of desmosome organization (GO: 0002934) and hemidesmosome assembly (GO: 00031581) in metastatic melanomas, including JUP, PKP3, KRT14, and KRT5, were inhibited." (PMID 29377892, 2018).
ovarian serous adenocarcinoma (1 paper, 2020). An adenocarcinoma that arises from the ovary and is characterized by the presence of malignant epithelial cells that, in well differentiated tumors, resemble the epithelium of the fallopian tube or, in poorly differentiated tumors, show anaplastic features and marked nuclear atypia. "The transcription level of PKP3 were significantly higher in ovarian serous adenocarcinoma than those in the normal tissues in Yoshihara’s dataset (Fold change = 62.784, P = 2.34E−09)." (PMID 33088217, 2020).
ovarian tumor (1 paper, 2025). "Another study revealed that circIGF2BP3 functioned as the molecular sponge of miR-328-3p and miR-3173-5p to upregulate plakophilin 3 (PKP3) expression, thereby increasing ovarian tumor (OTU) family deubiquitinase ubiquitin aldehyde binding 1 (OTUB1) level and facilitating PD-L1 deubiquitination." (PMID 40158127, 2025).
pemphigus vulgaris (1 paper, 2014). Pemphigus is a group of chronic autoimmune skin diseases characterized by blister formations on the outer layer of the skin and the mucous membranes. "Furthermore, PKP3 binds in vivo to several other primary pemphigus vulgaris autoantigens including DSG3, DSG1, DSC1, and DSC3." (PMID 24988487, 2014).
tumor (25 papers, 2010 to 2024). "The abnormal expression of PKP3 causes a loss of cell adhesion, which, in turn, produces highly active and invasive tumor cells, resulting in tumor metastasis." (PMID 37760912, 2023). "Mechanistically, PKP3 is not only involved in the modulation of different tumor-associated signaling pathways but also extensively inhibits the PC immune infiltration level, particularly the immune function of CD8+ T cells." (PMID 37760912, 2023). "Next, PKP3, encoding the protein plakophilin-3, improves upon both the leading clinical tumor selectivity and safety scores for HNSC (AUC = 0.89 and FDR p = 0.065; TB safety = 8.67; and HPA safety = 1.55)." (PMID 37835579, 2023). "Immune infiltration analysis was conducted in the present investigation to determine the association between PKP3 and tumor-infiltrating immune cells (TICs)." (PMID 37760912, 2023). "PKP3 loss leads to an increase in anchorage independent growth and an increase in tumor formation and metastasis in vivo." (PMID 25875355, 2015). "Plakophilin3 (PKP3) loss results in increased transformation in multiple cell lines in vitro and increased tumor formation in vivo." (PMID 25875355, 2015). "The increase in MMP7 levels is required for cell migration and invasion in vitro and tumor formation in nude mice as loss of MMP7 in the PKP3 knockdown cells results in a reversal of these phenotypes." (PMID 25875355, 2015). "The decrease in tumor size and metastasis suggest that K8 is required for transformation downstream of PKP3 loss." (PMID 22701666, 2012). "Consistent with the data that PKP3 is required for desmosome formation, PKP3 loss was associated with tumor progression and metastasis in tumors derived from the oral cavity and the colon." (PMID 22701666, 2012). "Our results also suggest that the increase in K8 levels is required, at least in part, to mediate the tumor progression and metastasis induced upon PKP3 loss." (PMID 22701666, 2012). "The loss of PKP3 expression was found to be correlated with poor prognistic clinicopathological features that increased node number and advance stage of tumor." (PMID 21194493, 2011). "There was no observable clinical association with PKP1 or PKP2 expression; however, low PKP3 level and poor prognosis appeared to correlate with regards to node number and tumor stage." (PMID 21194493, 2011). "The abnormal expression of PKP3 causes the loss of cell adhesion, which leads to the high activity and invasion of tumor cells, which separates some tumor cells from the primary tumor and realizes tumor metastasis." (PMID 38200443, 2024). "PKP3 may impact prognosis by broadly inhibiting immune cell infiltration and promoting the activation of tumor-associated signaling pathways." (PMID 37760912, 2023). "The results suggest that MMP7 over-expression may be one of the mechanisms by which PKP3 loss leads to increased cell invasion and tumor formation." (PMID 25875355, 2015). "Thus, the results in this paper suggest that the increased tumor formation observed upon PKP3 loss requires the expression of MMP7." (PMID 25875355, 2015). "PKP3 expression was significantly associated with nodal status and tumor size." (PMID 21194493, 2011). "Taken together, PKP3 is a tumor-associated gene that may suppress immune responses against tumors." (PMID 37760912, 2023). "In addition, PKP3 is involved in regulating malignant progression in PC patients, including lower levels of tumor differentiation and larger tumor volumes, which could partially explain the poor prognosis caused by PKP3." (PMID 37760912, 2023). "Previous results from our laboratory demonstrated that PKP3 loss leads to alterations in desmosome size, a decrease in cell-cell adhesion, increased cell migration and an increase in colony formation in soft agar and tumor formation and metastasis in immune-compromised mice." (PMID 25875355, 2015).
tumor (continued). "The elimination of tumor PD-L1 effectively nullified the influence of the circIGF2BP3/PKP3 axis on the CD8+ T cell response." (PMID 38638430, 2024). "CircRNA circIGF2BP3 stabilized OTUB1 mRNA and inhibited the ubiquitination and degradation of PD-L1 in a PKP3-dependent way, leading to tumor immune escape." (PMID 38638430, 2024). "PKP3 mRNA levels exhibited a significant increase in tumor tissues compared to normal tissues and displayed a positive correlation with FERMT1." (PMID 38200443, 2024). "Dysregulation of PKP3 in tumor cells leads to altered desmosome size, reduced intercellular adhesion, and increased cell migration, further contributing to tumor progression." (PMID 37760912, 2023). "PKP3 mRNA expression was heterogeneous among different tumor types but showed an increasing trend in most tumors, including PC." (PMID 37760912, 2023). "Our research suggests that PKP3 mediates the progression, migration, and invasive capabilities of PC cells, eventually leading to tumor progression and poor prognosis." (PMID 37760912, 2023). "The abnormal upregulation of PKP3 within PC tissues promotes tumor cell proliferation and metastasis, inhibits antitumor immunity, and ultimately leads to poor prognosis." (PMID 37760912, 2023). "Liu’s study found that circIGF2BP3 inhibited the anti-tumor immunity of NSCLC by increasing the expression of its targeted mRNA PKP3." (PMID 36139159, 2022). "Depending on the type of cancer, over-expression of PKP3 protein and PKP3 mRNA have been shown to have oncogenic and tumour suppressing effects." (PMID 34415821, 2022). "PKP3 plays some roles in the tumor microenvironment, such as regulating cell invasion and tumor formation via MMP7 proteins and regulating adhering junctions and mesenchymal-epithelial transitions by interaction with desmoglein and desmocollin." (PMID 35075375, 2022). "The deletion of PD-L1 in tumor entirely interrupted the effect of circIGF2BP3/PKP3 axis on response to CD8+ T cells." (PMID 36545327, 2022). "Tumor PD-L1 deletion completely blocked the impact of the circIGF2BP3/PKP3 axis on the CD8+ T cell response." (PMID 34416901, 2021). "The combination of PKP3 silencing and anti-PD-1 treatment led to a significant reduction in tumor burden compared with PKP3 knockdown or anti-PD-1 treatment alone." (PMID 34416901, 2021). "Taken together, these data confirmed that circIGF2BP3 promotes tumor immune escape by upregulating PKP3 expression in NSCLC cells." (PMID 34416901, 2021). "We further explored the regulatory effect of the circIGF2BP3/PKP3 axis on PD-L1 expression and its impact on tumor growth and antitumor immunity in vitro and in vivo." (PMID 34416901, 2021). "In this study, we determined that miR-328-3p and miR-3173-5p were sponged by circIGF2BP3, resulting in fewer miRNAs targeting PKP3 and thus suppressing tumor immunity." (PMID 34416901, 2021). "It’s suggested that PKP3 participated in RNA metabolism, gene post-transcriptional regulation and protein synthesis of tumor cells." (PMID 33088217, 2020). "Previous studies from our laboratory have demonstrated that loss of PKP3 in HCT116, HaCaT and FBM cells leads to an increase in transformation in vitro and increased tumor formation and metastasis in vivo." (PMID 25875355, 2015). "Our work has demonstrated that PKP3 loss leads to an increase in migration, invasion, tumor formation and metastasis and that these functions are dependent upon the increase in MMP7 expression upon PKP3 knockdown." (PMID 25875355, 2015). "Our results suggest that in HCT116 cells, the increase in MMP7 levels is driven by PRL-3 over-expression in the PKP3 knockdown clones and that MMP7 is required for tumor formation in-vivo upon PKP3 loss." (PMID 25875355, 2015). "A shRNA mediated decrease in K8 expression in the PKP3 knockdown clones leads to a decrease in migration, a decrease in colony formation in soft agar and decreased tumor size and metastasis in mice." (PMID 22701666, 2012).
tumor (continued). "In addition, the biological function of PKP3 is closely related to the Rap1 signaling pathway, PI3K–Akt signaling pathway, and MAPK signaling pathway, illustrating the prospective function of PKP3 in promoting tumor progression." (PMID 37760912, 2023). "The findings indicate that PKP3 functions as an oncogene that promotes tumor progression." (PMID 37760912, 2023). "Intriguingly, while the upregulation of PKP3 has been observed during the development of many cancer types, its potential tumor suppressive role has also been reported in HNSC, with its expression prognostically favorable, denoting a paradoxical role of it and other desmosomal proteins in HNSC." (PMID 37835579, 2023). "Exploring its mechanism revealed that circIGF2BP3 could specifically sponge miR-328-3p and miR-3173-5p, alleviating their inhibition of PKP3, thereby inducing tumor immunosuppression in NSCLC." (PMID 36139159, 2022). "Taken together, these results confirmed that circIGF2BP3 could specifically sponge miR-328-3p and miR-3173-5p, relieving their repression on PKP3 and thereby inducing a tumor immunosuppressive effect in NSCLC." (PMID 34416901, 2021). "Moreover, circIGF2BP3-mediated CCL5 downregulation in the tumor region was blocked following PKP3 silencing." (PMID 34416901, 2021). "Furthermore, PKP3 silencing significantly blunted circIGF2BP3 overexpression-mediated immunosuppressive effects, as determined by assessing the tumor volume." (PMID 34416901, 2021). "Moreover, we stratified patients from cohort I according to PKP3 abundance and the number of CD8+ TILs in the tumor region into three groups (group 1: low PKP3/high TILs; group 2: low PKP3/low TILs or high PKP3/high TILs; and group 3: high PKP3/low TILs)." (PMID 34416901, 2021). "Similarly, RNAi (small interference RNA) suppression of plakophilin 3 results in transformation of epithelial cells and accelerated tumor formation as well as lung metastasis in mouse tumor xenografts." (PMID 20953359, 2010). "Therefore, PKP1 and PKP3 play a tumor suppressor role in HNC." (PMID 34203070, 2021). "Thus, our data indicated that the PKP3-mediated effect is dependent on tumor PD-L1." (PMID 34416901, 2021). "Decreased PKP2 and PKP3 expression may be an early step in tumor transformation." (PMID 21194493, 2011). "Immune infiltration analysis demonstrated that PKP3 impeded CD8+ T-cell infiltration and immune cytokine expression within the tumor microenvironment." (PMID 37760912, 2023). "A previous report from our laboratory has demonstrated that a decrease in the levels of PKP3 in HCT116 cells, which are derived from the colon, led to an increase in colony formation in soft agar and increased tumor formation and metastasis in nude mice." (PMID 22701666, 2012). "The candidate substrates identified in our analysis (e.g. p120, integrin β4, plakophilin 3, STAT3 and vimentin) will inform future studies addressing the mechanisms involved in CSF-1R-induced tumor progression." (PMID 21049007, 2010). "PKP3 stabilizes PD-L1 by promoting PD-L1 deubiquitination mediated by the deubiquitinase OTUB1, and PKP3 can also increase OTUB1 mRNA stability and upregulate OTUB1 expression, both of which synergistically induce tumor immunosuppression." (PMID 36139159, 2022). "Moreover, although PKP3 overexpression significantly inhibited CD8+ TIL infiltration and boosted tumor growth and PD-L1 expression in the CTRL group, this effect was significantly blocked in the sgCD274 group." (PMID 34416901, 2021). "Moreover, immune profiling confirmed that the combination of PKP3 inhibition and PD-1 blockade significantly promoted the infiltration and activation of CD8+ T cells in the tumor region compared with that in any other group." (PMID 34416901, 2021). "IF staining and FACS analysis showed that PKP3 silencing was sufficient to abrogate the circIGF2BP3 overexpression-elicited decrease in the CD8+ TIL population and suppressed activated CD8+ T cells in the tumor region." (PMID 34416901, 2021).
tumor (continued). "Intriguingly, we found that the circIGF2BP3/PKP3 axis could also decrease the level of CCL5 in the TME, thus contributing to decreased CD8+ T cell recruitment into tumor regions." (PMID 34416901, 2021). "The results suggested that the level of PKP2 mRNA was associated with the tumor stages (P < 0.05), while the levels of PKP1 and PKP3 mRNA were not significantly different among the tumor stages (P > 0.05)." (PMID 33088217, 2020). "In addition, PKP3 could closely bind to RNA-binding proteins such as FXR1 and PABPC1, indicating that PKP1/2/3 can participate in cell connection and tumor progression through its interacting proteins." (PMID 33088217, 2020). "Also, it has been reported that p38β could be a critical step in tumor formation through regulation of lipocalin 2 (LCN2) expression, a direct target of Plakophilin 3 (PKP3)." (PMID 33053909, 2020). "Moreover, we could identify by transcriptome analysis several molecular markers involved in chemoresistance (TGM1, HSPAs, MT1s), cell‐adhesion and cell barrier (PKP3, CLDNs, PPL) that might help us to better understand the special characteristics of ascites‐derived tumor spheroids." (PMID 34060699, 2021). "qPCR analysis revealed that PKP3 expression in infiltrated CD8+ T cells was almost absent compared with that in LLC cells, indicating that the circIGF2BP3/PKP3 regulatory axis functions mainly in tumor cells." (PMID 34416901, 2021). "Interestingly, in the absence of PKP3, p38β is able to control the expression of LCN2, indicating a potential role of p38β in tumor formation." (PMID 33053909, 2020).